YY1 (YY1 transcription factor)
Description:
Multifunctional transcription factor that exhibits positive and negative control on a large number of cellular and viral genes by binding to sites overlapping the transcription start site. Binds to the consensus sequence 5'-CCGCCATNTT-3'; some genes have been shown to contain a longer binding motif allowing enhanced binding; the initial CG dinucleotide can be methylated greatly reducing the binding affinity. The effect on transcription regulation is depending upon the context in which it binds and diverse mechanisms of action include direct activation or repression, indirect activation or repression via cofactor recruitment, or activation or repression by disruption of binding sites or conformational DNA changes. Its activity is regulated by transcription factors and cytoplasmic proteins that have been shown to abrogate or completely inhibit YY1-mediated activation or repression. For example, it acts as a repressor in absence of adenovirus E1A protein but as an activator in its presence. Acts synergistically with the SMAD1 and SMAD4 in bone morphogenetic protein (BMP)-mediated cardiac-specific gene expression. Binds to SMAD binding elements (SBEs) (5'-GTCT/AGAC-3') within BMP response element (BMPRE) of cardiac activating regions. May play an important role in development and differentiation. Proposed to recruit the PRC2/EED-EZH2 complex to target genes that are transcriptional repressed. Involved in DNA repair. In vitro, binds to DNA recombination intermediate structures (Holliday junctions). Plays a role in regulating enhancer activation. Recruits the PR-DUB complex to specific gene-regulatory regions. Proposed core component of the chromatin remodeling INO80 complex which is involved in transcriptional regulation, DNA replication and probably DNA repair; proposed to target the INO80 complex to YY1-responsive elements.
Synonyms: INO80S; NF-E1; DELTA; UCRBP; YIN-YANG-1; GADEVS
Tractability: PROTAC: UniProt records ubiquitination sites on it; ubiquitination databases record sites on it; its protein half-life has been measured.
Gene: Protein-coding gene on chromosome 14 (100,238,298 to 100,282,788, forward strand). Ensembl gene ENSG00000100811.
Subcellular location: Nucleus matrix
Subcellular location (Human Protein Atlas): Nucleoplasm; Nuclear bodies; Nucleoli fibrillar center
Pathways (Reactome):
Developmental Biology: Activation of anterior HOX genes in hindbrain development during early embryogenesis; Differentiation of naive CD4+ T cells to T helper 2 cells (Th2 cells)
DNA Repair: DNA Damage Recognition in GG-NER
Gene expression (Transcription): TFAP2 (AP-2) family regulates transcription of growth factors and their receptors
Metabolism of proteins: UCH proteinases
Signal Transduction: Estrogen-dependent gene expression
Gene Ontology:
Molecular function: cis-regulatory region sequence-specific DNA binding; DNA binding; DNA-binding transcription activator activity, RNA polymerase II-specific; DNA-binding transcription factor activity, RNA polymerase II-specific; DNA-binding transcription factor binding; DNA-binding transcription repressor activity, RNA polymerase II-specific; four-way junction DNA binding; protein binding; RNA binding; RNA polymerase II cis-regulatory region sequence-specific DNA binding; sequence-specific double-stranded DNA binding; SMAD binding; transcription cis-regulatory region binding; DNA-binding transcription repressor activity; chromatin binding; DNA-binding transcription factor activity; lncRNA binding; promoter-specific chromatin binding; sequence-specific DNA binding
Biological process: cellular response to UV; chromatin remodeling; DNA damage response; double-strand break repair via homologous recombination; negative regulation of gene expression; negative regulation of interferon-beta production; negative regulation of transcription by RNA polymerase II; positive regulation of DNA-templated transcription; regulation of cell cycle; regulation of chromosome organization; regulation of DNA replication; regulation of DNA strand elongation; regulation of transcription by RNA polymerase II; response to UV-C; positive regulation of transcription by RNA polymerase II; B cell differentiation; cell development; cellular response to interleukin-1; chromosome organization; immunoglobulin heavy chain V-D-J recombination; negative regulation of cell growth involved in cardiac muscle cell development; negative regulation of miRNA transcription; positive regulation of DNA repair; positive regulation of telomere maintenance in response to DNA damage; regulation of DNA repair; and 5 more
Cellular component: fibrillar center; Ino80 complex; nuclear body; nuclear matrix; nucleoplasm; nucleus; PcG protein complex; transcription regulator complex; chromatin; chromatin silencing complex; ribonucleoprotein complex
Genetic constraint (gnomAD): Loss-of-function variants: 2 observed, 31.45 expected, observed/expected ratio (o/e) 0.0636, 90% interval 0.025 to 0.2. The upper end of that interval is the gene's LOEUF score, 0.2, which puts it in group 1 of 6, group 1 being the genes least tolerant of losing a copy. Missense variants: 322 observed, 553.71 expected, observed/expected ratio (o/e) 0.58, 90% interval 0.53 to 0.64. Synonymous variants: 268 observed, 237.37 expected, observed/expected ratio (o/e) 1.13, 90% interval 1.02 to 1.25.
Gene-disease validity (ClinGen):
ClinGen rates the evidence that YY1 causes each of these diseases.
complex neurodevelopmental disorder (autosomal dominant): Definitive. A disorder that involves more than one phenotype associated with the central nervous system, including but not limited to intellectual disability, autism, and seizures (epilepsy).
Homologues: Orthologues: chimpanzee YY1 (99% identical), macaque YY1 (99% identical), mouse Yy1 (99% identical), dog YY1 (98% identical), pig YY1 (98% identical), rat Yy1 (98% identical), tropical clawed frog yy1 (83% identical), zebrafish yy1a (76% identical), Drosophila melanogaster pho (42% identical). Paralogues in human: YY2 (54% identical), ZFP42 (36% identical).
Diseases named in the same sentence as YY1 in open-access papers:
YY1 is named in the same sentence as 277 diseases in open-access papers, as found by Europe PMC text mining. Sharing a sentence is not in itself a finding about the gene and the disease. The quoted sentences say what the papers report.
breast cancer (107 papers, 2008 to 2025). A primary or metastatic malignant neoplasm involving the breast. "Survival analyses showed that high YY1 levels were associated with a significantly worse OS in breast cancer patients." (PMID 41009346, 2025). "In breast cancer, overexpression of YY1 has been associated with decreased Flap Endonuclease 1 (FEN1) expression and increased sensitivity to chemotherapy drugs such as mitomycin C and Taxol." (PMID 41327312, 2025). "Our study provides novel findings about the association between YY1 and CP2c and its prognostic implication in breast cancer through quantitative analysis at the transcriptome and protein levels." (PMID 37444605, 2023). "The transcription factor YY1 is overexpressed in prostate, colon, liver, lung, and breast cancers, and its over-expression is associated with poor prognosis in patients with osteosarcoma and Acute Lymphoblastic Leukemia." (PMID 35740532, 2022). "The results of YY1 loss- and gain-of-function assays showed that YY1 fuels the migratory, invasive, colony-forming, and in vivo tumorigenic potentials of breast cancer cells." (PMID 33728560, 2021). "Overexpression of miR-372 blocked autophagy activation and inhibited breast cancer xenograft growth in vivo, underlining the importance of YY1-mediated miR-372 suppression and autophagy for cancer cell proliferation." (PMID 28459042, 2017). "Thus, we investigated YY1 expression in association with CP2c in breast cancer patients and their prognostic implications." (PMID 37444605, 2023). "Similarly, an infiltration for NKT cells has been reported in breast cancer, but this is the first mention of their association with CNVs in genomic regions affecting YY1 and PEBP1 to our knowledge." (PMID 37894300, 2023). "In the present study, it was found that YY1 overexpression was significantly associated with a better prognosis in patients with primary breast cancer, suggesting that the YY1 expression could be a potential prognostic biomarker." (PMID 37444605, 2023). "The signal pathway rewiring involving YY1 and CP2c might be important for breast cancer prognostics, and the mechanisms underlying this phenomenon remain to be solved." (PMID 37444605, 2023). "Further, YY1 has been shown to repress the expression of cell cycle inhibitor p27 and also has been shown to physically interact with p27 and cause its ubiquitination via Skp2 leading to unopposed growth of breast cancer cells." (PMID 31824839, 2019). "The development of a mathematical model combining YY1 as a molecular predictor with other prognostic factors in a comprehensive panel could significantly improve risk stratification and guide further clinical decisions in breast cancer." (PMID 41009346, 2025). "Despite the discrepancies reported in the literature, our findings provide strong evidence for nuclear YY1 expression as an independent prognostic factor for poor OS in breast cancer patients." (PMID 41009346, 2025). "One study identified YY1’s role as a cofactor of activator protein 2 (AP-2) to upregulate the oncogene ERBB2 in breast cancer cell lines." (PMID 41327312, 2025). "Another study showed overexpression of YY1 inhibits tumor formation in breast cancer by binding to the promoter of BRCA1 to positively regulate its expression." (PMID 41327312, 2025). "In contrast, the oncogenic role of YY1 has been widely recognized across various cancer types, though YY1 has been identified as a tumor suppressor in pancreatic cancer, breast cancer, and nasopharyngeal carcinoma." (PMID 41235100, 2025). "Yet, other studies have found that increased expression of YY1 in breast cancer cells inhibited cell proliferation, foci formation, and tumor growth in nude mice, and that YY1 can suppress the growth of various tumor cell types, including breast." (PMID 40867231, 2025). "In breast cancer, Ying Yang 1 (YY1), which is a kind of transcription factor/repressor also directly binds to the miR-140 promoter and promotes the expression of miR-140." (PMID 40895302, 2025).
breast cancer (continued). "In this study, we analyzed nuclear YY1 expression in a cohort of 276 Mexican women with breast cancer through tissue microarrays (TMAs), immunohistochemistry (IHC), and digital pathology (DP)." (PMID 41009346, 2025). "In breast cancer, elevated YY1 levels have been found to lead to FEN1 downregulation, increasing cancer cell sensitivity to mitomycin C or Taxol." (PMID 40867231, 2025). "YY1 promotes P27 ubiquitination and physically interacts with P27 in various breast cancer cell lines." (PMID 39796650, 2024). "In breast cancer, the oncoprotein-binding domain of Yin Yang 1 (YY1) has the ability to attract EZH2, leading to the downregulation of both phosphatase and tensin homolog (PTEN) and PTENP1." (PMID 38534385, 2024). "P27 is almost always degraded in cancer cell lines, showing how YY1 can increase the likelihood of breast cancer through this ubiquitination." (PMID 39796650, 2024). "When ectopically expressed in breast cancer cells, wild-type YY1 promotes cell proliferation significantly less than mutants with decreased dimerization propensity." (PMID 37686614, 2023). "YY1-conditional knockout destroys the ability of tumor formations in bladder and breast cancer cell lines through the inhibition of migration and invasion." (PMID 37686541, 2023). "These prognostic patterns of YY1 and CP2c expression in breast cancers were also observed in hepatocellular carcinoma (HCC) patients, but not in head and neck squamous cell carcinoma (HNSCC) patients." (PMID 37444605, 2023). "In line with this, two YY1-binding sites were identified upstream of the miR-372 transcription start site, and upregulation of miR-372 was found in siYY1 treated MCF-7 breast cancer cells (YY1 is known to be one of the key subunits of the INO80 complex)." (PMID 37445863, 2023). "Contrary to prostate cancer, breast cancer is characterized by an increased cellular zinc level, overly promoting YY1 dimerization and oligomerization." (PMID 37686614, 2023). "In one study, betulinic acid inhibited the growth of breast cancer cells through the downregulation of YY1." (PMID 37444616, 2023). "YY1 has been shown to be overexpressed in a variety of cancers including breast cancer, lung cancer, prostate cancer, and ovarian cancer." (PMID 37444605, 2023). "Some studies have demonstrated that YY1 overexpression in breast cancer cell lines leads to tumor promotion through the ERBB2 and Akt/Cyclin D1 pathways." (PMID 37444605, 2023). "It is known that the expression of YY1 is upregulated in breast cancer tissues as compared to that in adjacent normal tissues." (PMID 37444605, 2023). "This study aimed to investigate YY1 and CP2c expression in breast cancer and prognostic implications." (PMID 37444605, 2023). "RNF144A exerts a negative regulatory effect on the expression of GMFG in breast cancer by specifically targeting YY1-degrading proteasomes, thereby preventing the proliferation, migration, and invasion of breast cancer cells." (PMID 38259686, 2023). "Taken together, m6A-modified LINC00958 significantly promotes BC cell proliferation via the miR-378a-3p/YY1 axis, which indicates a potential target for breast cancer detection and treatment." (PMID 37069649, 2023). "Collectively, these findings reveal that RNF144A negatively regulates GMFG expression by targeting YY1 for proteasomal degradation, thus inhibiting the proliferation, migration, and invasion of breast cancer cells." (PMID 35103856, 2022). "The GATA2 TF is related to kidney and breast cancer-related pathway when the higher expression pattern of YY1 TFs increases the tumour size and higher TNM stage." (PMID 36016137, 2022). "Meanwhile, YY1 activated LINC00673 to reinforce breast cancer cell proliferation through the miR-515-5p/microtubule affinity regulating kinase/Hippo signaling pathway." (PMID 35778739, 2022).
breast cancer (continued). "A large number of experiments have proved that YY1 was highly expressed in many tumors, including breast cancer, prostate cancer, colon cancer, ovarian cancer, esophageal cancer, nervous system tumors, pancreatic cancer, osteosarcoma, and melanoma." (PMID 35791393, 2022). "Overall, our functional results of the YY1-OPB mutants suggested that disruption of OPB-mediated dimerization was beneficial to the overall proliferative activity of YY1 in breast cancer cells." (PMID 35406384, 2022). "TCGA database also showed that breast cancer patients or TNBC patients with high YY1 expression had shorter survival than those with low YY1 expression ones." (PMID 35383155, 2022). "Among various human cancer tissues, protein expression of YY1 was highest in head and neck tumors, followed by breast cancer." (PMID 35791393, 2022). "In this study, we found that YY1 transcriptionally activates GMFG expression, and RNF144A interacts with YY1 and promotes its degradation through the ubiquitin–proteasome pathway, thus blocking YY1-mediated induction of GMFG expression in breast cancer cells." (PMID 35103856, 2022). "LINC00673, which is upregulated by YY1, exerts oncogenic functions in breast cancer by sponging miR-515-5p and subsequently upregulates MARK4 expression, and inhibits the Hippo signaling pathway." (PMID 36309503, 2022). "In breast cancer, YY1 promotes the stemness, clonogenicity, migration, invasion, and tumor formation of breast cancer cells." (PMID 35103856, 2022). "Positively controlled by METTL3, LINC00958 promotes the tumorigenesis for breast cancer by regulating the miR-378a-3p/YY1 axis." (PMID 35676619, 2022). "YY1 and HP1α are both downregulated in invasive breast cancer cells and YY1 knockdown decreases the mRNA level of HP1α." (PMID 35159030, 2022). "The S118 site of YY1 showed a higher phosphorylation level in breast cancer, colon cancer, and UCEC and LUAD tumor tissues, and lower phosphorylation levels were found in ovarian cancer and clear cell carcinoma." (PMID 35791393, 2022). "The S118 site of YY1 showed higher phosphorylation levels in breast cancer, colon cancer, UCEC, and LUAD tumor tissues (all P < 0.05) and showed lower phosphorylation levels in ovarian and clear cell carcinomas (both P < 0.05)." (PMID 35791393, 2022). "Strikingly, the mutations of the hydrophobic residues showed better ability than wild-type YY1 in promote breast cancer cell proliferation and migration." (PMID 35406384, 2022). "High expression of YY1 is frequently observed in various cancers, including breast cancer, pancreatic cancer, colon cancer, and lung cancer." (PMID 35409160, 2022). "In the current study, the YY1(F219A) and (3A) mutants showed significantly improved binding to EZH2, with simultaneously increased breast cancer cell proliferation and migration, compared to wt YY1." (PMID 35406384, 2022). "The expression of YY1 was upregulated in many cancers, which might play a regulatory role in the activation, progression, and/or maintenance of malignant tumors in many tumor models and was associated with poor prognosis, including breast cancer, pancreatic cancer, prostate cancer, and colon cancer." (PMID 35359580, 2022). "For example, YY1 inhibits tumor proliferation in colon cancer and breast cancer but promotes tumor growth in melanoma, non-Hodgkin Lymphomas, and prostate cancer." (PMID 35359580, 2022). "High YY1 expression correlated positively with pathological progression and poor prognosis of high‐grade breast cancer." (PMID 35811688, 2022). "For instance, LINC00958 regulated by m6a modification can promote breast cancer tumorigenesis through miR-378a-3p and YY1 axis." (PMID 34026852, 2021). "METTL8 expression was up-regulated in most human breast cancer cell lines tested and decreased by Yin Yang 1 (YY1) transcription factor knockdown, suggesting that YY1 is a regulating transcription factor." (PMID 34063990, 2021).